CRP (C-reactive protein)
Diseases named in the same sentence as CRP in open-access papers (continued):
Sharing a sentence is not in itself a finding about the gene and the disease.
metabolic syndrome (continued). "Inclusion of affective status in the model of the association between CRP polymorphisms and metabolic syndrome did not influence the non-significant relationship." (PMID 21296145, 2011). "The aim of this study was to evaluate cardiovascular risk through the FRS, ultrasensitive CRP measurement and the presence of metabolic syndrome, among men with and without erectile dysfunction who were diagnosed within a continuing health review program." (PMID 20963365, 2010). "In a study observing no gender difference in CRP level, an association between CRP and metabolic syndrome had been reported as a whole and gender difference in the association between CRP and metabolic syndrome had not been explored." (PMID 20663138, 2010). "Moreover, Mediterranean-like diet was shown to reduce levels of CRP, IL-6 and IL-18 in a middle-aged population with the metabolic syndrome." (PMID 20331890, 2010). "CRP was reported to increase in metabolic syndrome and type-2 diabetes." (PMID 19222849, 2009). "Future studies including this parameter and other relevant biomarkers linked to the metabolic syndrome, e.g. interleukin (IL)-6, tumour necrosis factor (TNF)-α and C-reactive protein (using high-sensitivity assays), should assist in further interpretation of the data obtained." (PMID 19575082, 2009). "In clinical trials CRP elevation was related to metabolic syndrome and its components." (PMID 19222849, 2009). "Therefore, chronic inflammation and increase in CRP level are the common pathways in the metabolic syndrome and infectious agents for promotion of atherosclerotic process." (PMID 17140429, 2006). "The strong association observed between hs-CRP and dyslipidemia may be due to other contributing factors rather than a direct cause." (PMID 39859220, 2025). "Therefore, CRP was chosen as the primary marker in our analysis, as it is not only the most frequently reported but also provides a clear and direct reflection of inflammatory status in individuals with metabolic syndrome." (PMID 41245414, 2025). "Additionally, future research should consider adipose tissue parameters alongside other clinical variables—such as metabolic syndrome components, systemic inflammatory markers (e.g., CRP, IL-6), and genetic or epigenetic factors—to develop comprehensive, multifactorial risk prediction models." (PMID 40868344, 2025). "Additionally, integrating PIV with other inflammatory or metabolic markers—such as CRP, serum ferritin, or indicators of metabolic syndrome—could enhance its predictive accuracy and strengthen its utility in personalized medicine." (PMID 39935476, 2025). "We calculated glucose intolerance and assessed metabolic syndrome (MetS) and c-reactive protein (CRP) at 1-year postpartum." (PMID 41276872, 2025). "However, a significant adjusted association between CRP and dyslipidemia was observed in males (p < 0.001) but not in females (p = 0.005)." (PMID 39936780, 2025). "Furthermore, a positive correlation was observed between dyslipidemia and elevated hs-CRP levels." (PMID 39192929, 2024). "Furthermore, in a comprehensive risk factor study conducted among overweight children and adolescents, both ALT and hs-CRP (high-sensitivity C-reactive protein) were employed as screening indicators for assessing the presence of metabolic syndrome and cardiovascular disease risks." (PMID 39135800, 2024). "An RCT supplementing overweight adults at risk of metabolic syndrome (n = 45) with a GOS mixture (5.5 g/d) for 12 weeks, resulted in an increase in Bifidobacterium and a significant beneficial change in the immunomarkers, plasma C-reactive protein, and faecal calprotectin, compared to placebo." (PMID 39703540, 2024). "Hence, more prospective studies emphasizing the Framingham score change and C-reactive protein with patient follow-up are required to provide more detailed information on BBR’s efficacy in treating dyslipidemia, atherosclerosis, and overall cardiovascular benefit in the long run." (PMID 37346213, 2023).
metabolic syndrome (continued). "We assessed the prespecified secondary outcome metabolic syndrome severity z-score (MetS-Z), abdominal obesity (estimated as android fat via dual-energy X-ray absorptiometry), and inflammation marker high-sensitivity C-reactive protein (hsCRP)." (PMID 36841762, 2023). "However, in patients with dyslipidemia, triglyceride levels could vary up to 15 mmol/L, which could interfere with CRP quantification." (PMID 36662693, 2023). "It was also shown that a 3-month administration of a formulation containing piperine (at 5 mg) together with resveratrol (at 50 mg) and alpha tocopherol (at 25 mg) could alleviate inflammation by reducing levels of ferritin and C-reactive protein in individuals with metabolic syndrome." (PMID 37764345, 2023). "For instance, an 8-week co-administration of piperine (at 10 mg) with curcuminoids (at 1 g) could improve oxidative and inflammatory status by enhancing serum levels of SOD while reducing those of malonaldehyde (MDA) and C-reactive protein in individuals with metabolic syndrome." (PMID 37764345, 2023). "Patients with metabolic syndrome consuming the functional food made out of the indigenous consortium of bacteria cultivated on the artificial media demonstrated a significant improvement in several clinical and laboratory parameters such as BMI, body weight, CRP, ALT, and AST." (PMID 36013992, 2022). "It is unclear how the dietary patterns reflecting C-reactive protein (CRP) affect metabolic syndrome (MetS) in the Chinese population." (PMID 35807747, 2022). "Elevated CRP levels may also be predictive of development of the metabolic syndrome." (PMID 35844632, 2022). "The present study demonstrated that KBD had lower metabolic syndrome (MetS) and serum CRP concentrations, an inflammation index." (PMID 33546299, 2021). "These primary mediators in turn exact a secondary physiologic response ranging from metabolic (dyslipidemia, elevated glucose levels, and waist-hip ratio) to cardiovascular (increased blood pressure and heart rate variability) and inflammatory (C-reactive protein [CRP] and fibrinogen)." (PMID 34009131, 2021). "Studies based on pre-diagnostic CRP levels have shown that other (BMI, IL-6 in healthy but not overweight men, leukocytes, metabolic syndrome components) or multiple etiologies of chronic inflammation correlate with increased prostate cancer risk, but often not CRP individually." (PMID 34926085, 2021). "CRP might have a joint effect with metabolic syndrome in carcinogenesis." (PMID 34527591, 2021). "Presumably, this selection of biomarkers may not be specific enough to operationalize NAFLD, as they also reflect other metabolic pathways to T2DM, including chronic inflammation (CRP) and dyslipidemia (blood lipids), which may explain the unexpected results in this analysis." (PMID 34835937, 2021). "Also, we found a significant reduction of IL-6 and CRP in women with metabolic syndrome." (PMID 32256716, 2020). "Thus, metabolic syndrome is associated with pro-inflammatory cytokines such as TNF, IL-beta, and is characterized by chronic systemic low-grade inflammation manifested by elevated CRP." (PMID 31331009, 2019). "Furthermore, the authors found that elevated CRP levels could be regarded as an indicator of metabolic syndrome." (PMID 31372137, 2019). "Furthermore, combined use of ghrelin and inflammatory markers (IL-6, CRP) failed to explain the association between the metabolic syndrome and the cardiovascular mortality in older adults." (PMID 28100170, 2017). "Hence CRP can probably be used as a marker of chronic inflammation in metabolic syndrome patients." (PMID 27029038, 2016). "The relationship between the presence of metabolic syndrome and adiponectin level was evaluated by multiple logistic regression analysis with adjustments for age, sex, smoking status, body mass index, hemoglobin, serum albumin, uric acid, phosphate, hs-CRP, UACR, and eGFR." (PMID 27895721, 2016).
metabolic syndrome (continued). "It is also found that hs-CRP levels are correlated with metabolic syndrome (MetS), and endothelial dysfunction." (PMID 26193292, 2015). "Findings from our current study further corroborated previous reports that in the setting of hyperlipidemia, statins treatment not only could improve dyslipidemia, but also concomitantly decreased Rho kinase activity which consequently reduced CRP level and enhanced NO production." (PMID 25028180, 2014). "For instance, it has been reported that serum leptin is augmented in obese individuals with metabolic syndrome (MetS) that also show an elevation in the plasma levels of CRP." (PMID 23986664, 2013). "In the present study, higher levels of serum leptin concentrations were positively associated with the risk of developing metabolic syndrome in older women independent of potential confounders, measures of body fat distribution, proinflammatory cytokines, and CRP." (PMID 24455217, 2013). "However, when the model was adjusted for age, sex and traditional markers of adiposity such as BMI or waist circumference, HMW-adiponectin, but not CRP, was significantly associated with development of metabolic syndrome." (PMID 24069195, 2013). "However, the association between metabolic syndrome and CRP, but not HMW-adiponectin, was markedly attenuated after adjustment for age, sex and BMI or waist circumference." (PMID 24069195, 2013). "In univariate logistic regression analysis, both CRP and HMW-adiponectin were significantly associated with development of metabolic syndrome (odds ratio: 1.54 and 0.45 for MetS and 1.65 and 0.33 for JMetS, respectively)." (PMID 24069195, 2013). "It is indicated that exercise training reduced plasma CRP levels in CAD patients regardless of being with or without metabolic syndrome, drug therapy or weight gain or loss and they showed that effect of exercise on CRP is independent of weight loss and statin therapy." (PMID 23495361, 2012). "Thus, CRP and leptin may represent useful biomarkers for predicting the onset of cardiovascular disease or metabolic syndrome in Taiwanese adults." (PMID 22533665, 2012). "The aim of this study was to investigate the independent associations among cardiorespiratory fitness, metabolic syndrome (MetS), and C-reactive protein (CRP) in children." (PMID 22315623, 2012). "As there were no sex differences in CRP genotype or allele distribution, and sex by genotype interactions for both affective status and metabolic syndrome were not significant, the analysis of genetic associations are presented in the sample with men and women combined." (PMID 21296145, 2011). "Both of them identified significant association between CRP and metabolic syndrome and/or its components, but they did not examine whether there existed gender difference in this association." (PMID 20663138, 2010). "Thus CRP, ET-1,P-selectin, ICAM-1, and VCAM-1 levels are related to bothhyperglycemia and dyslipidemia and may reflect the presence of amultiple-risk factor clustering syndrome providing further supportfor the role of these markers in atherosclerosis." (PMID 17497038, 2007). "Probiotics can also benefit the heart by decreasing TMAO, LDL-c, TG, CRP, MDA, TNF-α, IL-6, and urea levels, improving dyslipidemia and toxin profiles." (PMID 40913714, 2025). "Conversely, LDL levels were positively correlated with both CRP (r = 0.38, p < 0.05) and TNF-α (r = 0.41, p < 0.01), suggesting that dyslipidemia contributes to heightened inflammatory activity in KOA patients." (PMID 40078412, 2025). "However, the causality between hs-CRP and dyslipidemia has not yet been explored using MR." (PMID 39859220, 2025). "Clinical studies also report reductions in circulating C-reactive protein (CRP) and improvements in antioxidant capacity following lutein supplementation in patients with metabolic syndrome and T2DM." (PMID 40563357, 2025).
metabolic syndrome (continued). "CRP is also recognized as one of the most significant markers in the development of CVD and metabolic syndrome." (PMID 40713717, 2025). "On the other hand, some egg studies have found that participants who were overweight or who had metabolic syndrome experienced a reduction in inflammatory markers after egg interventions (3 eggs/day for 4–12 weeks led to reductions in TNF-α, IL-6, and CRP)." (PMID 40647165, 2025). "Several studies have reported that copper levels are positively correlated with the inflammatory marker C-reactive protein (CRP), and other studies have established a link between elevated levels of inflammatory markers and dyslipidemia." (PMID 40172775, 2025). "The combination of CRP level and lipid indices, CRP/HDL-C, is applied in clinical practice as a predictor of metabolic syndrome." (PMID 40104822, 2025). "In patients with metabolic syndrome, the results presented by Alizaei Yousefabadi (2021) demonstrate a significant reduction in TNF-α, CRP, and IL-8 but an increase in IL-10 after a 12-week follow-up period." (PMID 40559680, 2025). "A cohort of 600 KOA patients was analyzed, revealing significant correlations between dyslipidemia (low HDL, high LDL) and inflammatory biomarkers (CRP, IL-6)." (PMID 40078412, 2025). "For women, the first variable selected was BMI≥29 kg/m2 followed by age ≥50, NC ≥36 cm, hs-CRP ≥0.2 mg/L, fasting glucose ≥94 mg/dL, HDL-c <42 mg/dL, dyslipidemia, and WC ≥109 cm." (PMID 40531757, 2025). "However, the relationship between hs-CRP and dyslipidemia remains unclear." (PMID 39859220, 2025). "This study investigates the subclasses of metabolic syndrome (Mets) and their relationship with non-alcoholic fatty liver (NAFLD) and the probable predictive role of serum vitamin D and CRP levels." (PMID 40093747, 2025). "The patients had dyslipidemia, mild increases in HOMA-IR, circulating creatinine, inflammatory biomarkers (hs-CRP, TNF-alpha, IL-6), and indicators of fibrosis (galectin-3 and sST2)." (PMID 40299414, 2025). "Age, HT, DM, dyslipidemia, BMI, LVEF, albumin, WBC, neutrophil, CRP, NLR, NPAR, and CAR, which were statistically significant in the univariate analysis, were included in the multivariate analysis." (PMID 41153281, 2025). "Patients in T3 group are more likely to have dyslipidemia, higher BMI, LDL-C, TG, TC, TG/HDL-C, Glu, UA, CRP, and lower HDL-C compared to the low TG/HDL-C group (P < 0.05)." (PMID 38566225, 2024). "Persistent low-grade inflammation, marked by elevated levels of inflammatory markers such as C-reactive protein (CRP) and interleukin-6 (IL-6), is common in individuals with metabolic syndrome." (PMID 39574946, 2024). "In a systemic review, a mild to moderate correlation between CRP levels and PWV (Pearson r = 0.33 to r = 0.624) was observed in individuals with dyslipidemia in most of the relevant studies." (PMID 38792880, 2024). "Subgroup analyses were categorized according to sample size, geographic region, and ferritin measurements and corrected for BMI, CRP, HOMA-IR, ALT, and metabolic syndrome criteria." (PMID 39410926, 2024). "RSV appears to consistently downregulate inflammatory markers, such as C-reactive protein and tumour necrosis factor-α, in a number of disease states, including T2DM, metabolic syndrome, and non-alcoholic fatty liver disease (NAFLD)." (PMID 38255828, 2024). "Recent studies also showed that dyslipidemia was related to higher levels of inflammatory markers, such as interleukin-6 (IL-6), tumor necrosis factor alpha-a (TNF-α), and C-reactive protein (CRP)." (PMID 38566090, 2024). "Low-grade inflammation plays a role in the pathogenesis of metabolic syndrome (MetS), and measuring levels of inflammatory molecules, such as high-sensitivity C-reactive protein (hs-CRP), may indicate Mets progression." (PMID 37537612, 2023).
metabolic syndrome (continued). "Elevated levels of pro-inflammatory cytokines, such as IL-6, CRP, and tumor necrosis factor (TNF)-α, have been observed in both periodontal disease and dyslipidemia." (PMID 37711924, 2023). "This included hyperglycemia, dyslipidemia (elevated TG and reduced HDL), oxidative stress (increased plasma 7α- and 7β-hydroxycholesterol), and heightened inflammation markers (hs-CRP and IL-1β) in the T2DM group." (PMID 37710315, 2023). "Significant differences (p < 0.05) between groups were observed for BMI, diastolic pressure, insulin, HOMA index, glycated hemoglobin (HbA1c), C-reactive protein, triglycerides, fatty liver index – FLI, and the presence of metabolic syndrome." (PMID 38034016, 2023). "Patients with liver steatosis showed a significant increase in BMI, diastolic pressure, insulin, HOMA index, glycated hemoglobin (HbA1c), C-reactive protein, triglycerides, fatty liver index (FLI), and the presence of metabolic syndrome." (PMID 38034016, 2023). "In adult patients with metabolic syndrome, a positive correlation of LAR levels with CRP has been described, suggesting that adipose tissue dysfunction is related to elevated LAR values." (PMID 36967781, 2023). "Females with dyslipidemia had higher TC, TG, FBG, HbA1c, UA, and CRP levels but lower mean HDL-C levels than those of females without dyslipidemia (all P < 0.05)." (PMID 38075062, 2023). "The association between hemoglobin levels and SSI in T2DM was also observed after additional adjustment for potential confounders: age, sex, HT, current smokers, dyslipidemia, ACR, BMI, phosphorus, TNFα, IL6, and hs-CRP." (PMID 37762433, 2023). "High glucose levels and dyslipidemia directly induce the upregulation and secretion of cytokines such as tumor necrosis factor-alpha (TNF-α), interleukins (IL-6, IL-1β), and C-reactive protein (CRP)." (PMID 37175496, 2023). "Experimental studies have demonstrated that elevated CRP leads to multiple features of metabolic syndrome, suggesting CRP might be an intermediate involved in the development of MetS." (PMID 35807747, 2022). "In the Women’s Genome Health Study, metabolic-syndrome related genes, such as LEPR, HNF1A, IL6R, and GCKR, were correlated to CRP expression and inflammation." (PMID 35845045, 2022). "In the female population, significant differences were observed in history of dyslipidemia, BMI, waist circumference, systolic and diastolic blood pressure, LDL-cholesterol levels, triglyceride levels, HOMA-IR, and hs-CRP level." (PMID 35619087, 2022). "Obtaining higher NLR scores, subjects were most likely to be the aged (> 65 years old), male, drinkers, obese (BMI > 30 kg/m2), or individuals with dyslipidemia, higher WBC count, and higher CRP level (within the normal range)." (PMID 35647067, 2022). "The relationship between CRP and dyslipidemia could be explained by excessive lipids accumulating in the arterial wall, inducing an inflammatory response; it accelerates lipid deposition and amplifies the inflammation producing inflammatory factors such as CRP." (PMID 35407457, 2022). "We aimed to prospectively evaluate the associations between the baseline and changes in high-density C-reactive protein (hs-CRP) and incident metabolic syndrome (MetS) in China and update the evidence based on a meta-analysis of cohort studies in different populations." (PMID 34991636, 2022). "Liver enzymes, C-reactive protein (CRP), interleukin-6, soluble intercellular adhesion molecule-1 (sICAM-1), adipokines, and parameters related to metabolic syndrome (MetS) were all measured." (PMID 33665176, 2021). "The common key molecules that link metabolic syndrome and psoriasis are TNF, IL-17, CRP, leptin, and adiponectin." (PMID 34207504, 2021). "Metabolic syndrome was more prevalent (p = 0.040) and IL6 levels were higher in the hs-CRP ≥3 group (p < 0.001)." (PMID 32514365, 2020).